RNU6-1117P (RNA, U6 small nuclear 1117, pseudogene)
Gene: Small nuclear RNA gene on chromosome 2 (35,471,605 to 35,471,708, forward strand). Ensembl gene ENSG00000207255.
Homologues: Orthologues: chimpanzee U6 (100% identical), macaque U6 (96% identical), pig U6 (93% identical), rabbit U6 (91% identical), pig U6 (88% identical). Paralogues in human: RNU6-1011P (94% identical), RNU6-38P (94% identical), RNU6-338P (93% identical), RNU6-1124P (92% identical), RNU6-12P (92% identical), RNU6-13P (92% identical), RNU6-25P (92% identical), RNU6-29P (92% identical), RNU6-32P (92% identical), RNU6-33P (92% identical), RNU6-41P (92% identical), RNU6-637P (92% identical), and 1288 more.